C2 (complement C2)
Diseases named in the same sentence as C2 in open-access papers (continued):
Sharing a sentence is not in itself a finding about the gene and the disease.
infection (53 papers, 2011 to 2025). The state of being infected such as from the introduction of a foreign agent such as serum, vaccine, antigenic substance or organism. "Among these proteins, in particular, TLR3 activated MSCs secreted TNFSF10, CXCL10, ISG15 and C2 (green highlight, 7C) were found upstream of several affected immune response and infection pathways in all 3 cell types." (PMID 40861855, 2025). "Consistently, the Lcn972R derivatives lysed when infected in broth with c2 at different multiplicities of infection (MOIs) and the percentage of inhibition was always higher, while lysis did not occur in IPLA1064." (PMID 40141150, 2025). "The expression of C2, C3, C5, C7, C8A, C8B, and C9 genes was found to be upregulated in the head kidney and spleen after infection in this study." (PMID 36835242, 2023). "While C2 almost fully blocked entry of SARS-CoV-2 pseudo-type at a concentration of 250 nM, F9-C2 and C2-foldon neutralized infection at 50 nM." (PMID 36067253, 2022). "This suggests that BYMV C2 protein is vital in infection as it involves symptom determination and the viral replication process." (PMID 34209952, 2021). "Further efforts are underway to elucidate the molecular mechanisms of GGVA infection by understanding the interaction between the host and V2, C2, and C4 proteins." (PMID 32983075, 2020). "The reduced expression of ABC transporters and peptidoglycan biosynthesis operons was also observed in Lactococcus lactis and Pseudomonas aeruginosa after infection with the c2 and PRR1 phages, respectively." (PMID 31285240, 2019). "Subsequently, the lytic mode of phage propagation was examined by monitoring the infection of LT2ΔpSLT/pALA2705 with an obligatory lytic P22 c2 parS (i.e. clear) mutant." (PMID 26720743, 2015). "We then showed that the critical factor in serum (diluted only 2-fold) that abrogated MBL's capacity to enhance infection is complement (specifically C2)." (PMID 23573288, 2013). "This might explain our observation that net4ab-c2 double mutants showed wild type-like bacterial growth upon infection with virulent Pto DC3000 and the disarmed Pto DC3000 cor- strain but showed increased bacterial growth of the non-virulent Pto DC3000 Hrc- strain." (PMID 37730720, 2023). "Therefore, we speculate that late in infection it is possible that C2 acts to derepress the promoter thereby producing CP at the appropriate time." (PMID 32508858, 2020). "The toxins that were accumulated in oysters in the experimental infection or in oyster individuals exposed in situ to natural A. catenella blooms can result from the transformation of some toxins (GTX3, C2 and others) produced by this dinoflagellate." (PMID 26784228, 2016). "A short lived ‘booster effect of infection’ was observed in the GERBUTM and Quil ATM groups while the highest level of in-vitro inhibition of C2 activity was observed for the IgGs from the Quil ATM group." (PMID 22621378, 2012). "Sixteen cattle complement genes, including complement C2, complement factor B (CFB), complement C1r (C1R), C1R-like, C3aR1, complement factor properdin (CFP) and complement factor I (CFI) were upregulated two- to 10.6-fold in response to the infection." (PMID 41398915, 2025). "In this study, we identified several proteins (FABP4, LEP, RARRES2, MSTN, C2, SELE and IL6) that belong to a family of chronic pro-inflammatory cytokines and are primarily produced in response to infection or stress, some of which are mainly produced by adipose tissue (FABP4, LEP and RARRES2)." (PMID 38548792, 2024). "Like the other NF-κB inhibitors, protein C2 and F3 are expressed early during infection and are non-essential for virus replication, but function within the cytosol to block the pathway downstream of receptors for TNFα and IL- 1β." (PMID 36301238, 2022). "In addition, we classified the patients into subgroups based on the infection with DENV-1 or DENV-2 and compared the levels of C2, C4b, C5, C5a, C9, factor D and factor I between these classified groups." (PMID 32913345, 2020).
infection (continued). "Capsid-deposited C4b neutralizes infection independent of C2 and C3 but requires C1q antibody engagement." (PMID 30926239, 2019). "Since they do not commit to lytic infection, such single copy P22 chromosomes are likely repressed and toggled by the C2 repressor, therefore remaining idle (as will be proven and discussed further below)." (PMID 26720743, 2015). "Despite the good results showed by the TiterMax group (good response, booster effect of infection and C2 inhibition), this adjuvant was not chosen for the cattle study since it was very expensive and not ideal for use in a cost-friendly anti-disease vaccine." (PMID 22621378, 2012). "Consequently the complement pathway functioning changes by increased expression of genes C2, C3, C4, CD55, and factor H, which may be needed as an early defence mechanism against dysbiosis/infection or a dysfunctional barrier." (PMID 37789352, 2023). "Moreover, C3, C5, C2, C1S, C4BPA (genes involved in the complement pathway) and SERPING1 (a regulator of complement activation) were significantly up-regulated, indicating an important role of the complement pathway in this infection." (PMID 34203742, 2021). "However, no HR develops during a typical TYLCSV infection, and co-expression of C2 with the Rep or V2 proteins partially counteracts the HR, resulting in chlorosis." (PMID 32508858, 2020). "Notably, C2-depleted MBL-replete serum enhanced infection maximally at a 50% dilution at which MBL's concentration was greatest, an effect that could be reversed by supplementation with recombinant human C2." (PMID 23573288, 2013). "Since TYLCCNV infection or expression of the TYLCCNV C2 protein failed to reverse transcriptional silencing or cytosine methylation at endogenous loci, betaC1 was proposed to functionally substitute for a loss-of-function mutation in the TYLCCNV C2 gene." (PMID 23887650, 2013). "Furthermore, a broad activation pattern of the complement system—encompassing both effector components (e.g., C2, C3, C8A, C9) and regulatory proteins (e.g., CFH, CFI, C1QB)—is consistent with prolonged innate immune stimulation in the absence of active infection." (PMID 40869330, 2025).
tumor (39 papers, 2010 to 2025). "Correlation analysis with tumor-associated fibroblasts showed that Egr1 + FibC1 and Scp2 + Fib-C2 were highly correlated with pan-iCAF-2 and pan-pCAF, respectively." (PMID 38753279, 2024). "In addition, to analyze the association of C2 expression with tumor-infiltrating immune cells, we also explore the underlying signaling pathways exploited by C2 to influence prognosis by KEGG analysis." (PMID 32626741, 2020). "In recurrent tumor tissues, the proportions of two distinct CAFs subsets (CAFs-c2-POSTN and CAFs-c1-MMP3) were significantly elevated." (PMID 40464813, 2025). "Box plots show increased expression levels of genes such as S100A1, C2, and SPP1, which are associated with tumor progression and metastasis." (PMID 41288989, 2025). "During our bioinformatics analysis, we found that C2 is not only expressed in tumor cells but also present in macrophages." (PMID 38473271, 2024). "The expressions of TIDE marker-genes were examined in each cell-type and found that C1 genes were mainly expressed in tumor cells, and C2 genes were highly expressed in monocytes, macrophages, fibroblasts, and endothelial cells." (PMID 38632658, 2024). "After effective immunotherapy, the upregulation of C2 expression, which is closely related to the tumor microenvironment, predicts better therapeutic efficacy and prognosis." (PMID 38473271, 2024). "Correspondingly, C2 signature was highly expressed in all tumors present with heterogenous expression across the tumor sections." (PMID 37414763, 2023). "The results showed that C2 expressions were lower than C1 expressions, indicating impaired antigen presentation for C2 tumor cells and an escape mechanism for C2 immune surveillance." (PMID 34222466, 2021). "ZIC2, ZIC5, and C2 overlap in the age-dependent tumor-normal difference and age-related tumor-tumor comparisons." (PMID 28027300, 2016). "Since both bulk tumor RNA-Seq and CyTOF data demonstrate increased infiltration of DCs after combination treatment, it is plausible to hypothesize that c2 migrated to the lymph nodes for antigen presentation after CpG+RT." (PMID 39133651, 2024). "Immune infiltrates corresponding to human tumor suppression and promotion, respectively, namely C1 (wound healing), C2 (INF-g dominant), C3 (inflammatory), and C4 (lymphocyte depleted), were applied to understand the connection between immune components and the risk signature." (PMID 34721986, 2021). "In addition, M2 macrophages synthesize C1q, a complement component that binds to the Fc portion of anti-tumor antibodies and triggers the classical component cascade in the presence of complement components such as C1r, C1s, C4, C2, C3 and C5 produced by tumor cells." (PMID 37622111, 2023). "Moreover, C2 exhibited more sensitivity to obatoclax, which might be due to obatoclax promoted tumor cells apoptosis by antagonizing WNT/β-catenin signaling that significantly was enriched in C2." (PMID 33552157, 2021). "Thus, individuals who have the KIR AA genotype in this population likely have two genomic copies of the strongly inhibiting KIR2DL1 allotype, KIR2DL1*003, and should be best equipped at recognizing and eliminating tumor cells having aberrant C2+HLA-C expression." (PMID 31379844, 2019). "We further quantified the number and strength of interactions between C2 GJA4+ Endothelial cells and other cell types, revealing extensive communication with other endothelial subtypes and tumor cells." (PMID 40639089, 2025). "In correlation with these, TAC tends to increase tumorigenic mTORC1/C2 activation and promotes proliferation in a cell-type dependent manner in epithelial and RCC cell lines, induced ischaemic kidneys, and RCC xenograft tumours as well." (PMID 38341510, 2024).
tumor (continued). "Cell types that are highly expressed in tumor tissues compared to normal tissues are CALM3+CD8+T cells-C1 and UGP2+Mac-C2 (p < 0.05)." (PMID 38361757, 2024). "C1r, C1s, C2, C3, C4b were increased in animals treated with combined radiotherapy and anti-C1-INH compared to control tumor, but the down-stream components in the classical pathway were not increased." (PMID 36717781, 2023). "Complement components that were most frequently upregulated in tumor tissues were CD46, C2 and complement factor B (CFB)." (PMID 33628739, 2020). "By contrast, the proportion of pro-tumor immune cells such as naive CD4+ T cells, activated dendritic cells, and resting NK cells were negatively correlated with the expression of several signature genes including C2, F2R, and C1QB." (PMID 37747262, 2023). "C1R, C2, C6, C8, MBL, CFP and CFHR were downregulated in HCC and exhibited tumour-suppressive effects; thus, they could serve as prognostic markers for HCC." (PMID 36341431, 2022). "Second, C2 expression is found to be associated with tumor-infiltrating cells, such as CD4 T cells and macrophage M0 cells, but we do not explore how C2 regulate these immune cells to influence the prognosis of HCC patients." (PMID 32626741, 2020). "Lastly, in the young.tumor versus old.tumor contrast, we identified five DEGs (ZIC2, ZIC5, ZNF439, USP54, and C2); this contrast may reflect differences in intrinsic tumor properties between tumors from the two age cohorts." (PMID 28027300, 2016). "Notably, C2 GJA4+ endothelial cells demonstrated strong signaling capabilities, engaging in extensive signal exchange with other endothelial cell subtypes and forming close connections with tumor cells." (PMID 40639089, 2025). "In addition, C2 overexpressed the dimNK-related marker FCGR3A, while C1 overexpressed the briNK-related marker XCL1 which has been shown to recruit conventional type 1 DCs to the tumour microenvironment." (PMID 36855107, 2023). "In addition, there is a negative correlation between the expression level of C2 and CD206+ macrophages in tumor tissue." (PMID 38473271, 2024).
cancer (36 papers, 2011 to 2026). A tumor composed of atypical neoplastic, often pleomorphic cells that invade other tissues. "Among them, TIMP1, LGALS3BP, A2M, AHSG, FN1, HRG, and ITIH4 have been associated with cancer, while CF I, C2, and C4A, have been related to complement activity." (PMID 37685286, 2023). "Specifically, according to canonical markers, the three quantity-predominant major components (i.e., c1, c2, and c4) were defined as cancer-associated myofibroblasts (CAFmyo), inflammatory CAFs (CAFinfla), and adipogenic CAFs (CAFadi) by over-presenting ACTA2, FAP/TGFB1, and CFD, respectively." (PMID 36333338, 2022). "A meta-analysis of 50 complement-related genes across 30 cancers reported high expression of classical pathway components, such as C4A and C2, including in BLCA, consistent with our results." (PMID 40283026, 2025). "In cancers including HCC, release of complement mediators such as C2 and C3 has been linked to macrophage polarisation and TIL functional reprogramming, raising questions as to their potential role as a therapeutic target for cancer immunotherapy." (PMID 37274775, 2023). "We noticed most checkpoint genes were up-regulated in fibroblast c2 and epithelial (malignant tumor)." (PMID 37954616, 2023). "HNRNPC, heterogeneous nuclear ribonucleoprotein C1/C2, is a commonly expressed RNA-binding protein with cancer-promoting function." (PMID 32984057, 2020). "We discovered that C2 inhibits multipolar spindle pole clustering, a survival mechanism employed by cancer cells with spindle abnormalities." (PMID 31652588, 2019). "The use of multiple targeting or dual-targeting agents (i.e. mTORC1/C2) to overcome feedback activation and resistance has garnered much interest in cancer research." (PMID 27015118, 2016). "In our previous review “PI3Kinase (PI3K)-AKT-mTOR and Wnt signaling pathways in cell cycle” we discussed the reciprocal relation between mTORC1 and C2 complexes in regulating cell metabolism and cell cycle progression in cancer cells." (PMID 23802099, 2013). "Notably, as expected, the COL1A1+/COL1A2+/IGFBP2+ fibroblast-like cells especially MSC-like-c2 present strong interactions with malignant tumor cells (MTC), which confirms our observation from in-house data." (PMID 37479733, 2023). "Understanding the full mechanism of action of C2 and testing its activity in various cancer types will allow analyzing whether the presence of multipolar spindles is a sole biomarker for C2 treatment." (PMID 31652588, 2019). "This indicates that C2 also targets cancer cells via a mitosis-independent mechanism." (PMID 31652588, 2019). "To strengthen this hypothesis we tested whether C2 can also target cancer cells from other tissues displaying elevated centrosome/centriole numbers, which should be prone to form multipolar spindles." (PMID 31652588, 2019). "Therefore, TGFβ induced Tie2-signal in CAF might act as a potential target against C2-CAF driven cancer cell reprogramming." (PMID 40349056, 2025). "In cultured human cancer cells, depletion of GβL/mLST8 has been shown to impair mTORC1 signaling, suggesting that GβL/mLST8 may have a role in cancer via modulating mTORC1/C2 complexes’ function." (PMID 41155718, 2025). "For instance, C2 expresses TIMP3, a metalloproteinase inhibitor that aids in the ECM remodeling, and NPNT, a gene reported to be related to development and cancer processes." (PMID 40111904, 2025). "For instance, C2 expresses TIMP3, a metalloproteinase inhibitor that aids in the extracellular matrix remodeling, and NPNT, a gene reported to be related to development and cancer processes." (PMID 39005414, 2024).
cancer (continued). "For example, C0 FXYD5+ TCs are abundantly present in cancerous tissues, whereas C2 MUC2+ TCs and C4 OTOP2+ TCs are predominantly present in normal and para-cancer tissues." (PMID 39717768, 2024).
bacterial infection (4 papers, 2010 to 2024). "Taken together these data suggest that recombinant human C2 can restore classical complement pathway activity and may serve as a potential therapeutic for recurring bacterial infections or SLE in C2-deficient patients." (PMID 20727163, 2010). "Among these genes, certain genes involved in the complement cascade were expressed at lower levels in the resistant family (c2, c6, cr1 or cd59), in contrast to what was found in head kidney samples after bacterial infection." (PMID 39712009, 2024).
immune disease (2 papers, 2021). "In KEGG, genes associated with immune disease and system include HLA-DQA1, HIST1H2BL, HIST1H2AL, C2, CFB, HSPA1A, TAP2, HIST1H3Jand ATP6V1G2." (PMID 34367251, 2021).
C2 also shares sentences with these, for which no sentence is quoted: atherosclerosis (6 papers); staphylococcus aureus infection (3); age (2); influenza (2); metabolic syndrome (2); Obesity (2); prostate carcinoma (2); prostate tumor (2); psoriasis (2); abdominal aortic aneurysm (1); acute myeloid leukaemia (1); alcoholism (1); Alzheimer disease (1); amyloidosis (1); angioedema (1); anorexia nervosa (1); anthrax (1); asplenia (1); cardiac hypertrophy (1); cardiovascular disease (1); Cataplexy (1); celiac disease (1); cerebral malaria (1); chronic lymphocytic leukemia (1); Cirrhosis (1); congenital hydrocephalus (1); dermatomyositis (1); diabetic retinopathy (1); diphtheria (1); endotoxemia (1).
A further 43 diseases each share a sentence with C2 in 1 paper.